POLR3D (RNA polymerase III subunit D)
Description:
DNA-dependent RNA polymerase catalyzes the transcription of DNA into RNA using the four ribonucleoside triphosphates as substrates. Specific peripheric component of RNA polymerase III (Pol III) which synthesizes small non-coding RNAs including 5S rRNA, snRNAs, tRNAs and miRNAs from at least 500 distinct genomic loci. Assembles with POLR3E/RPC5 forming a subcomplex that binds the Pol III core. Enables recruitment of Pol III at transcription initiation site and drives transcription initiation from both type 2 and type 3 DNA promoters. Required for efficient transcription termination and reinitiation (By similarity). Pol III plays a key role in sensing and limiting infection by intracellular bacteria and DNA viruses. Acts as nuclear and cytosolic DNA sensor involved in innate immune response. Can sense non-self dsDNA that serves as template for transcription into dsRNA. The non-self RNA polymerase III transcripts, such as Epstein-Barr virus-encoded RNAs (EBERs) induce type I interferon and NF-kappa-B through the RIG-I pathway.
Synonyms: BN51T; TSBN51; RPC4; C53; RPC53
Tractability: Small molecule: a structure with a bound ligand is known. PROTAC: UniProt records ubiquitination sites on it; ubiquitination databases record sites on it; its protein half-life has been measured.
Gene: Protein-coding gene on chromosome 8 (22,245,094 to 22,254,601, forward strand). Ensembl gene ENSG00000168495.
Subcellular location: Nucleus
Subcellular location (Human Protein Atlas): Nucleoplasm
Pathways (Reactome):
Gene expression (Transcription): RNA Polymerase III Abortive And Retractive Initiation; RNA Polymerase III Chain Elongation; RNA Polymerase III Transcription Initiation From Type 1 Promoter; RNA Polymerase III Transcription Initiation From Type 2 Promoter; RNA Polymerase III Transcription Initiation From Type 3 Promoter; RNA Polymerase III Transcription Termination
Immune System: Cytosolic sensors of pathogen-associated DNA
Gene Ontology:
Molecular function: chromatin binding; DNA binding
Biological process: positive regulation of innate immune response; positive regulation of interferon-beta production; termination of RNA polymerase III transcription; transcription by RNA polymerase III; transcription initiation at RNA polymerase III promoter; tRNA transcription by RNA polymerase III
Cellular component: nucleoplasm; nucleus; RNA polymerase III complex; cytosol
Genetic constraint (gnomAD): Loss-of-function variants: 39 observed, 41.65 expected, observed/expected ratio (o/e) 0.94, 90% interval 0.72 to 1.22. The upper end of that interval is the gene's LOEUF score, 1.22, which puts it in group 5 of 6, group 1 being the genes least tolerant of losing a copy. Missense variants: 490 observed, 481.72 expected, observed/expected ratio (o/e) 1.02, 90% interval 0.94 to 1.1. Synonymous variants: 209 observed, 186.99 expected, observed/expected ratio (o/e) 1.12, 90% interval 1 to 1.25.
Homologues: Orthologues: chimpanzee POLR3D (100% identical), macaque POLR3D (99% identical), rat Polr3d (94% identical), dog POLR3D (94% identical), mouse Polr3d (94% identical), guinea pig POLR3D (94% identical), rabbit POLR3D (93% identical), pig POLR3D (92% identical), tropical clawed frog polr3d (64% identical), zebrafish POLR3D (55% identical), Drosophila melanogaster Polr3D (25% identical).
Diseases named in the same sentence as POLR3D in open-access papers:
POLR3D is named in the same sentence as 6 diseases in open-access papers, as found by Europe PMC text mining. Sharing a sentence is not in itself a finding about the gene and the disease. The quoted sentences say what the papers report.
leukodystrophy (3 papers, 2023 to 2025). Leukodystrophies are a group of rare, progressive, metabolic, genetic diseases that affect the brain, spinal cord and often the peripheral nerves. "Here, we describe the first reported case of POLR3-related leukodystrophy caused by biallelic pathogenic variants in POLR3D, encoding the RPC4 subunit of Pol III." (PMID 37915380, 2023). "This work identifies biallelic pathogenic variants in POLR3D as a novel genetic cause of POLR3-related leukodystrophy, expanding the molecular spectrum associated with this disease, and proposes altered tRNA homeostasis as a factor in the underlying biology of this hypomyelinating disorder." (PMID 37915380, 2023). "In the last few years, our group has identified and validated eight genes causative for leukodystrophy, including POLR3A, POLR3B, POLR1C, POLR3D, EPRS1, VARS1, and ABHD16A." (PMID 39062571, 2024). "POLR3-HLD, also termed 4H (Hypomyelination, Hypodontia, and Hypogonadotropic Hypogonadism) leukodystrophy, is caused by biallelic pathogenic variants in genes encoding subunits of the ubiquitous RNA polymerase III (Pol III) enzymatic complex (e.g., POLR3A, POLR3B, POLR1C, POLR3K, and POLR3D)." (PMID 39062571, 2024).
breast carcinoma (1 paper, 2021). "This suggests SL inhibition of POLR3D could be explored as an avenue in DDR-deficient breast cancers." (PMID 33992077, 2021).
metastatic tumor (1 paper, 2024). "The expression level upregulation of the genes might be mediated by TFs, such as POLR3D, NOTCH1 and ETS1, which were widely expressed at high levels in bone metastatic tumor samples." (PMID 38462627, 2024).
cancer (4 papers, 2018 to 2023). A tumor composed of atypical neoplastic, often pleomorphic cells that invade other tissues. "This epigenetic mechanism could be relevant in cancer since the POLR3D gene product is a component of the RNA polymerase III, whose abnormal activity is characteristic of cancer cells." (PMID 29401683, 2018). "A number of shared SNVs (53, including PTEN, POLR3D, STAG2) with an average cancer cell fraction of ~1 suggest cluster A as the Most Recent Common Ancestor (MRCA)." (PMID 37628903, 2023).
POLR3D also shares sentences with these, for which no sentence is quoted: genetic diseases (1 paper); infection (1).